TLR7 (toll like receptor 7)
Diseases named in the same sentence as TLR7 in open-access papers (continued):
Sharing a sentence is not in itself a finding about the gene and the disease.
lupus (continued). "Moreover, real-time PCR results showed that the mRNA levels of TLR7 were significantly higher in peritoneal macrophages from lupus mice than those of control mice." (PMID 27537524, 2016). "TLR7 is also considered to be an important contributor to the development of human lupus." (PMID 27050763, 2016). "Mechanistically, miR-146a acts as a negative regulator of type I IFN production by targeting multiple signaling components downstream of TLR7/9 and the retinoic acid-inducible gene-I pathways, thus its downregulated expression in lupus leukocytes promotes IFN-α production." (PMID 27509492, 2016). "Meanwhile, the expression of TLR7 was also increased in splenic macrophages from lupus mice." (PMID 27537524, 2016). "Exposure to TLR9 agonist CpG-DNA (and not to TLR7 agonists) induced anti-dsDNA IgG and ICs deposition and was associated with the onset of glomerulonephritis in lupus-prone mice." (PMID 27635115, 2016). "This comparison eliminated contributions of non-sex chromosome-linked lupus susceptibility genes while emphasizing potential effects of the Yaa-determined Tlr7 duplication." (PMID 27050763, 2016). "In this study, we show that pDCs are indispensable for the TLR7-mediated development of I-IFN-associated psoriasis-like skin inflammation and lupus-like systemic autoimmune disease under the intrinsic Siglec-H-mediated control of inflammation and T-cell responses." (PMID 27075414, 2016). "Furthermore, polymorphisms in TLR3, TLR7 and TLR9 genes have been associated with lupus patients in some populations and a number of in vivo and in vitro studies have strongly implicated a number of TLRs to play a role in the pathogenesis of lupus." (PMID 27846842, 2016). "Similarly, in a separate mouse model of lupus-like autoimmunity in which TLR7 expression is increased via a transgene, autoantibody production was dependent on the GC response and on TLR7 action in B cells." (PMID 27303636, 2016). "In lupus models, B cell-intrinsic TLR7 expression drives GC formation and autoantibody production." (PMID 26322049, 2015). "Lupus-prone mice deficient in both TLR7 and TLR9 or in their adaptor protein MyD88 do not develop either autoantibodies or lupus nephritis." (PMID 26322049, 2015). "Our previous study showed that TLR7 is necessary for disease development in pristane-induced lupus." (PMID 26717913, 2015). "In support of this idea, altered cellular levels of PRRs can cause autoimmunity in mammals, as illustrated by duplication of the Tlr7 gene in mice, which results in systemic autoimmunity modelling the clinical symptoms seen in the human autoimmune disease systemic lupus erythematosus (SLE)." (PMID 25709093, 2015). "In addition to driving autoantibody production, TLR7 engagement is likely to contribute to the pathogenesis of inflammatory disease in lupus." (PMID 26029213, 2015). "Moreover, blockage of TLR7 or TLR7/9 pathway with immunoregulatory sequences attenuates lupus pathogenesis in MRL-Faslpr/lpr mice." (PMID 26068236, 2015). "In contrast, pristane-induced lupus exhibits a prominent TLR7-dependent interferon signature." (PMID 26097482, 2015). "Moreover, TLR8−/− TLR7−/− mice show ameliorated lupus pathogenesis as well as restored MZ B cell population, indicating a critical function of TLR8 in controlling TLR7 activation." (PMID 26068236, 2015). "Intriguingly, they found that both global and DC-specific Tcf4 haplodeficiency abolished splenomegaly and myeloid cell expansion and diminished anti-RNA autoantibody levels in the presence of Tlr7 overexpression, which suggests a profound involvement of pDCs in this lupus model." (PMID 26528288, 2015). "However, ligation of TLR7 and 9 by self RNA and DNA in pDCs from lupus patients conferred increased survival and resistance of the pDC to glucocorticoid-mediated death." (PMID 24839407, 2014).
lupus (continued). "On the other hand, the activation of pDCs through TLR7/9 by ICs stimulates the nuclear factor κB (NF-κB) pathway essential for pDC survival, which undermines the effectiveness of high-dose steroid treatment owning to the resistance by lupus pDCs." (PMID 25077037, 2014). "Our results suggest that IL-4 could inhibit the TLR7-9 pathogenic steps and decrease the production of the IFN Signature in lupus." (PMID 24489947, 2014). "Thus TLR7/9 stimulation promoted secretion of pro-inflammatory cytokines in lupus prone mice, potentially as a result on the expansion MZ pDCs." (PMID 25093822, 2014). "Because TLR7 is associated with lupus, we suspect that EBV may contribute to IFN production in lupus patients." (PMID 22952664, 2012). "Lupus-prone mice deficient in TLR-7 also failed to generate antibodies against RNA-containing antigens such as Smith, which decreased lymphocyte activation and serum IgG." (PMID 22312407, 2012). "Because aberrant TLR7 activation is associated with lupus pathogenesis, high LMP1 expression in lupus might be related to the fact that TLR7 stimulates LMP1 expression in tissue cultured cells." (PMID 22952664, 2012). "In addition, treatment of lupus-prone mice with a dual inhibitor of TLR-7 and TLR-9 leads to the reduction of autoantibody production and amelioration of disease symptoms." (PMID 21860649, 2012). "In addition, the downstream signaling components of TLR7, IFN regulatory factor 5 (IRF5) and IRF7, are closely associated with lupus pathogenesis." (PMID 22952664, 2012). "In lupus-like mice, activation of TLR7/9 led to a strong upregulation of TACI." (PMID 21818370, 2011). "Notably, activation of TLR7-induced signaling is associated with higher IFN-α production in females and the peak time frame for lupus onset in women coincides with an increase in IFN-α activity." (PMID 20526365, 2010). "Refinement of the class R INH-ODN structure to combine optimal TLR7/TLR9 sequences in double-stranded carrier may result in a novel class of pathway-specific therapeutics for human lupus." (PMID 19476613, 2009). "Indeed, promising results have been reported in animal models of lupus using TLR7- and/or TLR9-specific antagonists." (PMID 19476613, 2009). "It has been reported that TLR7-deficient, lupus-prone mice failed to generate antibodies to RNA-containing antigens." (PMID 18652679, 2008). "TLR9 and TLR7 also had modulatory effects on clinical disease in lupus-prone mice." (PMID 18652679, 2008). "Increased TLR7 signaling has been reported in SLE patients and various mouse models of lupus‐like disease." (PMID 41574968, 2026). "Furthermore, deficiency of Bank1 in TLR7-transgenic (TLR7Tg) mice leads to a reduction in age-associated B cells (ABCs) and in an IFN-stimulated gene expressing B cell population, otherwise, increased in the TLR7Tg.Bank1+/+ lupus mice." (PMID 40761803, 2025). "For example, aberrant activation of TLR7 and TLR9 has been linked to the pathogenesis of systemic lupus erythematosus (SLE)." (PMID 41488647, 2025). "We next examined whether blocking TLR7 could attenuate these pathological changes in lupus mice." (PMID 41511304, 2025). "In systemic lupus erythematosus (SLE, lupus), endosomal toll like receptors (TLRs), TLR7 and TLR9, that sense (self) RNA and DNA, respectively, by signaling via activation of MyD88, initiate the loss of self tolerance and control disease severity." (PMID 40794441, 2025). "Systemic lupus erythematosus (SLE) is characterized by significant mitochondrial dysfunction, where mitochondrial damage releases mtRNA that can be recognized by TLR7, subsequently triggering type I IFN responses." (PMID 41293166, 2025). "Toll-like receptors (TLRs), especially TLR7, play an important role in systemic lupus erythematosus (SLE) pathogenesis." (PMID 38429401, 2024). "Crossing of kika mice with MyD88-knock-out mice completely rescued the lupus-like phenotype, further supporting the role of the TLR7–MyD88 signaling axis in SLE pathogenesis." (PMID 38255243, 2024).
lupus (continued). "The recent discovery of a lupus-causing gain-of-function TLR7 variant (Y264H) represents the most compelling and human-relevant evidence that enhanced TLR7 signaling is involved in SLE pathogenesis." (PMID 38255243, 2024). "Given the importance of TLR7 signaling in driving human lupus, phase II clinical trials evaluating the efficacy and safety of orally administered enpatoran in SLE and cutaneous lupus erythematosus have been initiated (NCT05162586, NCT05540327)." (PMID 38772735, 2024). "While the reasons that underly the sex-biased role of Tlr7 in pSD are unknown, studies in the lupus field demonstrate that Tlr9 plays a key role in regulating Tlr7-driven immune activation, as Tlr9−/− lupus mice show exacerbated disease that is ameliorated when Tlr7 is also deleted." (PMID 39310226, 2024). "Increased TLR7 activation was reported in B cells from the majority of SLE patients and TLR7 gain-of-function was subsequently identified as a cause of human monogenic form of lupus." (PMID 38866437, 2024). "Consistent with our hypothesis, Acod1−/− mice exposed to a TLR7 agonist, a lupus relevant stimulus, displayed disruptions in the splenic architecture, increased serum anti-dsDNA and IL-6, higher kidney immune complex deposition and proteinuria, when compared to the WT IMQ-treated mice." (PMID 38605883, 2024). "A similar beneficial role of RS in suppressing lupus-like pathogenesis in Toll-like receptor 7 (TLR7)-dependent mouse models of systemic lupus erythematosus (SLE) has been reported." (PMID 36854801, 2023). "Furthermore, TLR7-dependent monocytosis occurs in lupus-prone NZBWF1 mice." (PMID 37462944, 2023). "Additionally, estrogen stimulation of CD11b+ monocytes derived from C57BL/6 female mice culminated in the enhanced expression of Unc93b1, a molecular chaperone required for TLR7 activity and splenocytes from lupus-prone female mice expressed higher levels of Unc93b1 as compared to C57BL/6 controls." (PMID 39916928, 2023). "pDCs produce IFN-α via TLR7 as PRR and TNF-α and IL-6 via TLR9 in response to single-stranded RNA and double-stranded DNA, respectively, and may be associated with inflammatory/autoimmune skin diseases including psoriasis and lupus." (PMID 37629154, 2023). "In general, B cells may play a more crucial role in CD4+ T cell activation in lupus, at least partly due to their chronic activation via the self-antigen-induced stimulation of endosomal TLR7 and TLR9 receptors mediated by the adaptor myeloid differentiation primary response protein 88 (MyD88)." (PMID 38137363, 2023). "The endosomal Toll-like receptor 7 (TLR7) is a major driver of murine and human systemic lupus erythematosus (SLE)." (PMID 37606042, 2023). "Indeed, administration of an antibody against TLR7 that could block TLR7 signaling protected lupus-prone NZBWF1 mice from nephritis and inhibited autoantibody production." (PMID 36389822, 2022). "On the other hand, it predicted the emergence of systemic lupus erythematosus (SLE)-like biomarkers in severely ill COVID-19 patients due to an overactive TLR7-signaling pathway in a later phase of the disease." (PMID 35065665, 2022). "Mounting evidence indicates the importance of aberrant Toll-like receptor 7 (TLR7) signaling in the pathogenesis of systemic lupus erythematosus (SLE)." (PMID 35371102, 2022). "Moreover, Lactobacillus reuteri exacerbated lupus-related pathogenesis in TLR7-dependent Mice." (PMID 35677055, 2022). "In addition, HFD further increased TLR7 expression and signaling in TLR8 knockout mice (a spontaneous murine lupus model characterized by increased TLR7 signaling) leading to exacerbated kidney inflammation due to increased production and renal deposition of autoantibodies." (PMID 35069526, 2021).
lupus (continued). "To address the question whether microbiota from lupus mice induced by TLR7 activation might affect BP and endothelial function regulation, we transplanted microbiota for 2 weeks from hypertensive IMQ or from normotensive CTR animals to recipient BALB/c female mice or 8 weeks IMQ-treated mice." (PMID 34573058, 2021). "Considering that IL-17a is a crucial component in the mechanisms responsible for endothelial dysfunction in this TLR7-driven lupus autoimmunity model, our group then focused on the possible changes induced by DMB on the SLE-linked endothelial dysfunction." (PMID 35052589, 2021). "Apart from being involved in TLR9 and TLR7 signaling in DCs, it was recently demonstrated that CatK produces cleaved TLR7 in vitro, and in Tregs implicating CatK in blocking Treg immuno-suppressive activity and in promoting the development of murine systemic lupus erythematosus-like manifestations." (PMID 34335582, 2021). "Single-cell transcriptome data of female patients with either systemic lupus erythematosus (SLE) or COVID-19 revealed Xist dysregulation and overexpression of TLR7 in PBMCs and atypical B cells." (PMID 34858409, 2021). "The increase in IRF5 expression after activation with anti-IgM, anti-CD40, and R848 in vitro suggested the possibility that IRF5 might be increased in GC B cells in FcγRIIB−/−Yaa mice in vivo, because TLR7 activation is thought to be important for spontaneous GC formation in other lupus models." (PMID 34197340, 2021). "The presence of nucleic acids in the cytoplasm due to ineffective clearance activates endosomal TLR7 and TLR9; this is a major cause of systemic lupus erythematosus (SLE)." (PMID 34434197, 2021). "Thus, ABC expansion and lupus pathogenesis in DKO females are dependent on Tlr7." (PMID 34376664, 2021). "Moreover, both AMP-activated protein kinase (AMPK) agonist metformin and two mammalian targets of rapamycin (mTOR) inhibitors (INK128 and rapamycin) inhibited the percentage of M-MDSCs in lupus mice as well as in the TLR7- and IFN-α-induced bone marrow (BM) differentiation into MDSCs in vitro." (PMID 34282122, 2021). "However, examination of allelic expression of putative disease-causing candidate genes like Tlr7 failed to reveal major differences in biallelic cell frequencies between B cells from lupus-prone and wild-type mice." (PMID 33498655, 2021). "On the other hand, aberrant activations of TLR7 and TLR9 have been implicated in type I IFN-related autoimmune diseases, such as systemic lupus erythematosus (SLE), which is characterized by the presence of autoantibodies against nucleic acids." (PMID 32708595, 2020). "IRS869, IRS661, and IRS954 represent such TLR7 and 9-inhibitory iODNs that were recently proposed for the treatment of another autoimmune disease, namely systemic lupus erythematosus (SLE)." (PMID 31913271, 2020). "miR-3148 levels were inversely correlated with Toll-like receptor 7 (TLR7) transcript levels in peripheral blood monocytes obtained from systemic lupus erythematosus (SLE) patients." (PMID 32922961, 2020). "While TLR7 has been extensively studied in murine lupus, much less is known about its role in the pathogenesis of human SLE." (PMID 31231380, 2019). "Self-nucleic acids in lupus can be presented in the form of autoantibody immune complexes, membrane-coated microparticles, neutrophil extracellular traps (NETs) or oxidized mitochondrial DNA, and can induce TLR7/9-dependent B cell activation and IFN-I production by pDCs and follicular DCs." (PMID 30199535, 2018).
lupus (continued). "The up-regulation of TLR-7 in patient with SLE and TLR-7 activation in wild-type mice leads to lupus-like systemic autoimmune disease with elevated levels of autoantibodies and multiple organ involvement." (PMID 29988544, 2018). "The prevailing concept in SLE and murine lupus models is that immune complexes containing autoantibodies bound to self-DNA and RNA can act as interferogenic stimuli, following Fc receptor-mediated internalization and activation of endosomal TLR7 and TLR9 in pDCs." (PMID 29559975, 2018). "While the pathological role of TLR7 in human SLE and lupus nephritis in murine models is relatively accepted, the role of TLR9 remains controversial." (PMID 30210502, 2018). "For example, systemic lupus erythematosus (SLE)-like phenotype is spontaneously induced in BXSBYaa mice, which harbor an additional copy of the Tlr7 gene on Y chromosome." (PMID 29988708, 2018). "However, deletion of TLR7 in Wiskott-Aldrich syndrome protein (WASp) in mice inhibited systemic autoimmunity, whereas deletion of TLR9 promoted systemic autoimmunity which recapitulates the phenotype seen in TLR7/9-deficient lupus mice." (PMID 28456914, 2017). "In this study, we used TLR7-deficient (Tlr7−/−) mice and atherogenic diet-fed Apoe−/− mice to test whether TLR7 deficiency affects atherogenesis differently from Apoe−/− mice not on an atherogenic diet or mice on a Faslgld/gld lupus background." (PMID 28405010, 2017). "However, pDC-specific TLR7 or TLR9 deficiency in lupus-prone mice has not been reported, as B cells and some other innate immune cell types also express TLR7 and TLR9." (PMID 27034965, 2016). "TLR7 and TLR8 are encoded by X-linked genes, which may render females more susceptible to lupus." (PMID 26068236, 2015). "Endosomally located TLRs of DCs, such as TLR7, are involved in the tissue inflammation of autoimmune diseases, such as systemic lupus erythematosus (SLE)." (PMID 23497717, 2013). "New therapeutic approaches for SLE and lupus-like syndromes would be better directed on modifying Foxp3 expression by interfering with TLR7 activation or by blocking downstream effector cytokines such as IL-6." (PMID 21860649, 2012). "Recently, two TLR, namely, TLR7 and 9 have been connected to both human and mouse models of SLE and lupus-like syndromes where they act synergistically with BCR to induce B-cell proliferation." (PMID 21860649, 2012). "We will compare and contrast the roles of TLR7 and TLR9 in lupus and SjD, with a focus on the importance of B cell activation in disease." (PMID 42112403, 2026). "Many functional studies also implicate the TLR7 pathway in SLE pathogenesis in both human and murine lupus models." (PMID 40051623, 2025). "The effect of E6742, a dual inhibitor of TLR7 and TLR8, is stronger than that of either one alone in lupus mice." (PMID 40491969, 2025). "Endosomal toll-like receptors (TLRs) TLR7, TLR8, and TLR9 play an important role in systemic lupus erythematosus (SLE) pathogenesis." (PMID 39858436, 2025). "E6742, a selective dual antagonist for TLR7/8, has been investigated in a double-blind phase 1/2 study in SLE, and 57.1% of patients achieved a positive response on the British Isles Lupus Assessment Group-based Composite Lupus Assessment (BICLA), compared with 33.3% in the placebo group." (PMID 40746538, 2025). "“Toll-like receptor 7 and TLR9 dictate autoantibody specificity and have opposing inflammatory and regulatory roles in a murine model of lupus” by SR Christensen is the reference with the second largest citation count of 35 in this cluster." (PMID 40584714, 2025). "To study the role of Bank1 in the intestinal lupus pathology, we used two TLR7-dependent lupus models, the inducible (IMQ-mediated) and the spontaneous TLR7 transgenic lupus models." (PMID 40761803, 2025). "coli protein in the liver and normalized the enhanced expression of TLR-7, p-NFκB/NFκB, SOD1 and SOD2 induced by lupus." (PMID 41595543, 2025).